ZFHX4 (zinc finger homeobox 4)
Diseases named in the same sentence as ZFHX4 in open-access papers (continued):
Sharing a sentence is not in itself a finding about the gene and the disease.
renal cell carcinoma (1 paper, 2022). "Third, although this study found that four genes (COL7A1, LCTL, NPR3, and ZFHX4), had a large impact on the prognosis of renal cell carcinoma and analyzed their relationship with survival in multiple cancers, the specific molecular biology and cell biology mechanisms need to be further investigated." (PMID 36159988, 2022).
respiratory failure (1 paper, 2024). The significant impairment of gas exchange within the lungs resulting in hypoxia, hypercarbia, or both, to the extent that organ tissue perfusion is severely compromised. "Indeed, ablation of Zfhx4 leads to early postnatal lethality linked to respiratory failure, suggesting it plays an important role in early development." (PMID 39609254, 2024).
rhabdoid cancers (1 paper, 2023). "Although increased ZFHX4 expression is documented in the HPA database (accessed on 10 May 2023) for several cancer types, it is higher in bone (including OS-derived cell lines) and rhabdoid cancers." (PMID 37445641, 2023).
sarcoma (1 paper, 2022). A usually aggressive malignant neoplasm of the soft tissue or bone. "The 1-year AUC values for TCGA training cohort of the SAGRI constructed using the four sarcoma-like differentiation-related genes (COL7A1, LCTL, NPR3, ZFHX4) were 0.725 in the training set, 0.712 in the internal validation set, and 0.770 in the external validation set." (PMID 36159988, 2022).
tumor (31 papers, 2014 to 2025). "In the TWM cases, except case 1, ARID3A, ASXL1, ASXL2, FMN2, FAM83B and ZFHX4 mutations were also identified as potential oncogenic drivers, known from other tumor types." (PMID 36980598, 2023). "Although ZFHX4 took an active part in promoting cancer metastasis, it functioned as a tumor suppressor in tumor proliferation." (PMID 35915456, 2022). "Thirdly, the interpretation of these data was without consideration of which cellular compartment expresses ZFHX4, since whole tumor samples were sequenced in GSE73168." (PMID 35915456, 2022). "Non-sense variant p.E1996* and missense variant p.A1014D in tumor suppressor ATM are predicted as driver mutations according to OncodriveMUT, whereas alterations in gene ZFHX4 are predicted to be a passenger mutation." (PMID 34136393, 2021). "Compared with the control group, the tumor volume and tumor weight were smaller in the sh-TWIST1/sh-SLC12A5/sh-ZFHX4 groups." (PMID 31645542, 2019). "The ZFHX4 protein is a key molecular regulator of tumor-initiating stem cell-like function." (PMID 40281612, 2025). "As shown in the waterfall plot, there are variations in the tumor mutational burden (TMB) of two subtypes, and the frequencies of TTN, CSMD3, MUC16, RYR2, LRB1P and ZFHX4 mutations in the high-risk group were considerably higher than those in the low-risk group." (PMID 38345559, 2024). "In addition, we performed the expression profiles of significantly mutated genes in one normal group and two tumor groups; we identified 20 DEGs; among them CSMD3, DCHS2, LRP2, RYR2, and ZFHX4 were significantly negatively correlated with PFS." (PMID 35975176, 2022). "It is tempting to propose that further investigating the function of zfh2 in the Drosophila intestinal lineage will generate new hypotheses regarding the role of ATBF1 and ZFHX4 in tumor formation and progression." (PMID 31841513, 2019). "In addition, ZFHX4 was overexpressed in tumor tissues compared to normal controls, and knockdown of ZFHX4 in vitro significantly inhibited cell migration and invasion." (PMID 28694483, 2017). "The expression of ZFHX4 was widely altered in tumor tissues." (PMID 28694483, 2017). "The inconsistency in ZFHX4 regulation between different cancer types may indicate the complex mechanism of ZFHX4 in tumor biology." (PMID 28694483, 2017). "The genes with the highest influence are the transmembrane protein TMEM14A in the untreated tumor samples, the zinc-finger transcription factor ZFHX4 following 14 days of letrozole treatment, and the redox protein CYB5R3 following 90 days of letrozole treatment." (PMID 24495353, 2014). "In addition, we performed the expression profiles of significantly mutated genes between the normal group and tumor groups and identified 20 differentially expressed genes (DEGs); among them, CSMD3, DCHS2, LRP2, RYR2, and ZFHX4 were significantly negatively correlated with PFS." (PMID 35975176, 2022). "Comparing the primary tumor with one of the spinal lesions, eight genes were differentially expressed, with IFITM1 and ZFHX4 being notable due to their described roles in cancer metastasis." (PMID 36937401, 2023). "Knockdown of ZFHX4 decreased migratory and invasive abilities of ESCC cell lines indicating a tumor-promoting ability in ESCC." (PMID 32974170, 2020). "We used our own LUAD tissue microarray containing 92 pairs of LUAD and matched non-tumor tissue samples with clinicopathologic information and long-time follow-up records to evaluate the clinical utility of TWIST1, SLC12A5 and ZFHX4 among the LUAD patients." (PMID 31645542, 2019).
tumor (continued). "Accordingly, SLC12A5 was highly expressed in 17 out of 24 TWIST1 strong tumor tissue samples, and in 5 out of 18 tumor tissue samples with weak TWIST1 expression; ZFHX4 was highly expressed in 19 out of 24 TWIST1 strong tumor tissues, and in 6 out of 18 tumor tissue samples with weak TWIST1." (PMID 31645542, 2019).
cancer (19 papers, 2015 to 2026). A tumor composed of atypical neoplastic, often pleomorphic cells that invade other tissues. "Other cancer genes frequently altered in LC according to cBioPortal (e.g., ZFHX4, RYR2, CSMD3, FAT3, and RP1L1) were also found mutated at a high frequency in our cohort." (PMID 30925779, 2019). "Zinc finger homeobox 4 (ZFHX4) also had variants identified in two patients who died from cancer." (PMID 37445641, 2023). "From these, seven died from cancer (including the two who also had point mutations in ZFHX4)." (PMID 37445641, 2023). "We further examined the prognostic role of ZFHX4 mutations in 12 cancer types in TCGA." (PMID 28694483, 2017). "More interestingly, in vitro studies correlate over-expression of another zfh2 homolog, ZFHX4, with cancer cell migration and invasiveness." (PMID 31841513, 2019). "Interestingly, TCI revealed functional impact of certain SGAs with very high alteration frequencies, such as TTN, CSMD3, MUC16, RYR2, LRP1B, and ZFHX4, whose roles in cancer development remain controversial." (PMID 31276486, 2019). "Thus, more research is needed to further reveal the important roles of ZFHX4 in the progression of cancer." (PMID 28694483, 2017). "Furthermore, expression of ZFHX4 was widely dysregulated in many cancer types, indicating the significance of ZFHX4 in cancer." (PMID 28694483, 2017). "We identified two cancer cell lines, HGC27 and PC3, with CSMD3 and ZFHX4 amplification respectively, and we knocked down the expression of the two genes using siRNAs, followed by monitoring cellular phenotypes." (PMID 31276486, 2019). "TCI indicated that CSMD3 and ZFHX4 are 4th and 12th most frequent SGA-FIs, and yet, they are designated as cancer drivers in previous studies." (PMID 31276486, 2019). "To further demonstrate the important role of ZFHX4 gene in cancer, we examined the gene-expression profile of ZFHX4 in Chinese ESCC and 12 cancer types in TCGA." (PMID 28694483, 2017). "Similarly, there are no reports of an involvement of ZFHX4 in cancer predisposition." (PMID 25855136, 2015). "The top 15 SGA-FIs connected with CSMD3 and ZFHX4 also form densely connected networks that include well-known cancer drivers, such as KRAS, GATA3, KEAP1, ERBB2 and STK11, suggesting that alteration of CSMD3 and ZFHX4 may perturb some of the same signaling pathways as do these known drivers." (PMID 31276486, 2019). "As a new candidate gene of cancer, the functionality of ZFHX4 is not well studied." (PMID 28694483, 2017). "However, the role of ZFHX4 in cancer has not been well studied, especially in ESCC." (PMID 28694483, 2017).
neurodevelopmental disorder (1 paper, 2019). A behavioral and cognitive disorder with onset during the developmental period that involves impaired or aberrant development of intellectual, motor, or social functions. "Interestingly, four of these LoF variants disrupted genes previously implicated in neurodevelopmental disorders: KAT6A (c.1599-56_1621del in proband 10), SETBP1 (c.1781del, p.P594Lfs*36 in proband 13), TNRC6B (c.2040G>A, p.W680* in proband 15) and ZFHX4 (c.3646-1G>A in proband 14)." (PMID 29463886, 2019). "A significant number of these genes (CHD3, SETD1A, KAT6A, SETBP1, TNRC6B, ZFHX4, ARID1A and TRIO) have been associated with neurodevelopmental disorders with or without speech problems." (PMID 29463886, 2019).
skeletal dysplasia (1 paper, 2021). Any Mendelian diseases that affects growth and development of the skeleton. "On the basis of the skeletal phenotype of Zfhx4-deficient mice, this mutation induces rhizomelic type skeletal dysplasia." (PMID 34732852, 2021). "The Zfhx4 mutation described in the present study may be a good model to evaluate the pathogenesis of rhizomelic type skeletal dysplasia and such assessment might provide insights into the pathogenesis of rhizomelic dysplasia." (PMID 34732852, 2021).
ZFHX4 also shares sentences with these, for which no sentence is quoted: breast carcinoma (2 papers); glioma (2); Intellectual disability (2); prostate adenocarcinoma (2); anaplastic large cell lymphoma (1); apraxia (1); atrial fibrillation (1); bladder cancer (1); breast invasive carcinoma (1); Burkitt lymphoma (1); esophageal cancer (1); gastric cancer (1); hairy cell leukemia (1); head and neck squamous cell carcinoma (1); Hodgkins lymphoma (1); language disorder (1); lung squamous cell carcinoma (1); metastatic colorectal cancer (1); Micrognathia (1); microphthalmos (1); ovarian serous cystadenocarcinoma (1); Peters anomaly (1); pilocytic astrocytoma (1); pineal region tumor (1); prostate carcinoma (1); rectum adenocarcinoma (1); stomach adenocarcinoma (1).